CDH1 (cadherin 1)
Diseases named in the same sentence as CDH1 in open-access papers (continued):
Sharing a sentence is not in itself a finding about the gene and the disease.
lung adenocarcinoma (continued). "In order to investigate the effects of CDH1 and lncRNA H19 on the proliferation and apoptosis of lung adenocarcinoma cells, we transfected the previously constructed plasmids into A549 cells, followed by sphere‐forming assay, CCK‐8 assay and flow cytometry." (PMID 31317666, 2019). "One of the key findings of our study was that silencing of lncRNA H19, overexpression of CDH1 or reducing CDH1 methylation suppressed proliferation, migration and invasion, promoted apoptosis of lung adenocarcinoma A549 cells and inhibited the EMT." (PMID 31317666, 2019). "We determined methylation of CDH1 in 60 cases of lung adenocarcinoma tissues and 60 cases of adjacent tissues using MSP assay." (PMID 31317666, 2019). "We found that lung adenocarcinomas exhibited an epithelial CDH1high/VIMlow gene expression profile compared with normal lung tissues, demonstrating higher CDH1 in eight of nine data sets but lower VIM in all nine data sets." (PMID 27456471, 2016). "PRKAR1A mRNA was correlated with CDH1 expression in lung adenocarcinoma tissues (r = 0.3814, P < 0.0001)." (PMID 27995993, 2016). "Both H19 and CDH1 methylation were upregulated in lung adenocarcinoma tissues." (PMID 38355574, 2024). "Cdh1 expression is elevated in 17/33 human cancer types anaylazed, including lung adenocarcinoma." (PMID 32015681, 2020). "First, the oncogene function of Cdh1 overexpression in most cancers including lung adenocarcinoma has been uncovered by bioinformatic analysis and data mining of publically available cancer clinical databases, including GEPIA, Oncomine, TCGA, GEO and Kaplan-Meier plotter." (PMID 32015681, 2020). "LncRNA H19 and methylation of CDH1 were highly expressed in lung adenocarcinoma tissues." (PMID 31317666, 2019). "The results showed that compared with the normal lung cell line HFL1, among the lung adenocarcinoma cell lines, A549 cell line had the highest lncRNA H19 expression and the second lowest CDH1 expression (A549 cell line only slightly higher than PC9 cell line; P > .05)." (PMID 31317666, 2019). "Here, we tried to investigate whether lncRNA H19 or CDH1 methylation could affect the development of lung adenocarcinoma." (PMID 31317666, 2019). "It was concluded that silencing of lncRNA H19, overexpression of CDH1 or inhibition of CDH1 methylation could suppress migration and invasion of lung adenocarcinoma cells." (PMID 31317666, 2019). "First, lung adenocarcinoma tissues were collected to detect CDH1 methylation." (PMID 31317666, 2019). "We hypothesize that lncCDH5-3:3 controls CDH1 and, as a consequence, EPCAM expression, which encodes EpCAM, one more protein involved in the regulation of EMT, thereby exerting an important influence on the progression of lung adenocarcinoma." (PMID 35159188, 2022). "To conclude, the present study demonstrated that silencing of lncRNA H19 inhibited EMT and proliferation while promoting apoptosis of lung adenocarcinoma cells via inhibition of methylation of CDH1 promoter, which may provide a novel molecular target for treatment of lung adenocarcinoma." (PMID 31317666, 2019). "Furthermore, we found that silencing of lncRNA H19 could inhibit methylation of CDH1 promoter in lung adenocarcinoma." (PMID 31317666, 2019). "MiRNA hsa-mir-30a and lncRNA AC104472.1 constituted regulatory module for lung adenocarcinoma a with TPI1, KPNA2, MET, HSP90B1, P4HB, DSP, CDH1, and ENO1." (PMID 36138770, 2022). "Hsa-mir-145 formed the third regulatory module for lung adenocarcinoma c with lncRNA C1orf220, which ranked second in potential lncRNAs, and mRNAs (COL1A2, COL3A1, SPP1, TIMP1 and CDH1)." (PMID 36138770, 2022). "The effects of CDH1 and lncRNA H19 on EMT‐related factors in lung adenocarcinoma cell line A549 were further detected by immunofluorescence." (PMID 31317666, 2019).
lung adenocarcinoma (continued). "We characterized three lung adenocarcinoma cell lines H1299, H2291, and H1975 for their EMT status by immunofluorescence (IF) staining with canonical EMT markers - CDH1 (E-cadherin) and VIM (Vimentin)." (PMID 27008704, 2016). "To validate these observations, we quantified the expression of ZEB1, CDH1 and VIM for 41 paired samples of lung adenocarcinoma and adjacent normal lung tissues." (PMID 27456471, 2016). "Expression of TWIST1, mesenchymal (CDH2, VIM, SNAI1, ZEB1) and epithelial (CDH1, JUP) markers in lung adenocarcinoma cell lines." (PMID 22272264, 2012). "CDH1 is a widely known proto oncogene in the occurrence and development of cancer, while a relatively new oncogenic determinant MET regulates the occurrence, progression, and malignancy of epithelial carcinomas including lung adenocarcinoma." (PMID 36138770, 2022). "For investigation into the effects of CDH1 and lncRNA H19 on the EMT process, we further performed scratch test and Transwell assay to ascertain whether silencing of lncRNA H19, overexpression of CDH1 or inhibition of CDH1 methylation could affect migration and invasion of lung adenocarcinoma cells." (PMID 31317666, 2019). "We studied a series of consecutive lung adenocarcinoma from Caucasian non-smokers for which surgical frozen samples were available (n = 33) and showed that TWIST1 expression was linked to EGFR mutations (P<0.001), to low CDH1 expression (P<0.05) and low disease free survival (P = 0.044)." (PMID 22272264, 2012).
metastatic tumors (131 papers, 2002 to 2025). "In human PC, CDH1 hypermethylation and E-cadherin loss is more frequent in metastatic tumors with higher Gleason score." (PMID 31850082, 2019). "The ROC analyses, even performed on a limited number of samples, identified the cut-off levels of CDH1, CDH5, and ZEB1 genes useful for the possible diagnostic identification of primary or metastatic tumors." (PMID 40332096, 2025). "In this study, even though the high expression of miR-200c-3p was found to cause downregulation of a tumor suppressor gene DLC1, at the same time it also led to upregulation of CDH1 expression in both primary and metastatic tumor cells." (PMID 34071861, 2021). "Whilst numerous retrospective clinical studies of EAC have correlated low CDH1 or E-cadherin expression with metastatic disease and poor survival, our study is the first to provide functional in vivo evidence of this process." (PMID 27863424, 2016). "All recipient mice remained clinically well after an average of 100 d, but contained numerous ZSG+/Cdh1+/Icam1+ donor-cell clusters within their lungs, liver, kidneys and peritoneum at a frequency similar to metastatic tumors formed by tail-vein injections of tCZCs." (PMID 36175792, 2022). "The remaining two cases with pathogenic mutations were diagnosed with late stage metastatic disease and did not appear to be diagnosed as a result of being a known CDH1 mutation carrier." (PMID 29589180, 2019). "In contrast, the two CDH1 mutation carriers who did not appear to be known carriers were both diagnosed with late-stage metastatic disease and both died shortly after diagnosis." (PMID 29589180, 2019). "The low prevalence of CDH1 or CTNNB1 mutations in primary carcinomas suggested that mutations in these genes likely did not play much of a role in any metastatic disease that developed from these tumors." (PMID 29156750, 2017). "Moreover, CDH1 was observed to be progressively downregulated in sequence parenchyma, non-metastatic tumor, metastatic tumor and metastases and also significantly correlated with stage, grade and survival in RCC patients." (PMID 27549611, 2016). "Consistently, IHC/IF results showed that CDH1 and ZHX2 protein levels were negatively correlated in both mouse and human primary and metastatic tumors." (PMID 37460540, 2023). "Expression levels of miR-200a, miR-200b, miR-429, miR-30a-5p, miR-30a-3p, miR-30e, miR-30e-3p, CDH1, SLC22A24, C3orf52 and FREM1 were significantly decreased in metastatic (TNM stage III with pN+ and IV) compared to non-metastatic tumor (TNM stage I and II)." (PMID 27549611, 2016). "In clinical samples, further analysis demonstrated that there was a significant negative correlation between TRERNA1 and CDH1 in metastatic tumour cases." (PMID 31012192, 2019). "Notably, there was a much higher negative correlation between FABP12 and CDH1 mRNA levels in metastatic tumors (r = −0.66, P = 0.002) than in primary tumors (r = −0.25, P = 0.004)." (PMID 33031638, 2020).
lobular carcinomas (119 papers, 2003 to 2026). "Studies have shown that the abnormality of CDH1 gene and the loss of expression of membrane E-cadherin are common in the lobular carcinoma of the breast." (PMID 39049123, 2024). "Lobular carcinoma of the breast shows a loss of E-cadherin expression due to loss of the CDH1 gene on chromosome 16." (PMID 39184723, 2024). "It is worth mentioning that in three of the four lobular breast carcinoma cases, CDH1 loss has been detected." (PMID 37239898, 2023). "E-cadherin exhibits strong circumferential membranous staining, except in lobular carcinoma, in which there is loss of staining due to mutation of the CDH1 gene." (PMID 35784659, 2022). "As expected, CDH1 was significantly decreased in lobular carcinomas vs. ductal carcinomas in all 16q-loss groups (A, B1, and D) and was the only 16q-LvsD-DEGs that was coherently decreased in lobular carcinomas of those three groups." (PMID 33808143, 2021). "Out of the 18 Japanese GC individuals with germline CDH1 variants, 11 had family histories of cancers, and one had a lobular breast carcinoma, consistent with a germline variant of CDH1." (PMID 34267306, 2021). "CDH1 mutations were more common in the old group giving them the characteristic of late onset, alongside with the known CDH1 link with the lobular carcinoma phenotype." (PMID 33168853, 2020). "Loss of function mutations of the CDH1 gene, which result in impaired E-cadherin protein expression, are commonly detected in lobular breast carcinomas and diffuse gastric cancers." (PMID 32714931, 2020). "The diagnosis of lobular carcinoma was confirmed by immunohistochemistry (loss of expression of E-cadherin), and by targeted next generation sequencing, which identified a CDH1 mutation." (PMID 30153845, 2018). "IntClust 3 is enriched for CDH1 mutations, and this is secondary to the association with lobular carcinoma." (PMID 29532008, 2018). "IntClust 3 was enriched for tubular and lobular carcinomas, the latter largely accounting for the association with CDH1 mutations in this cluster." (PMID 29532008, 2018). "Inactivating mutations in CDH1 were observed in 52.6% of lobular carcinomas, and CDH1 was also the most frequently mutated gene in lobular carcinomas in the TCGA data set34." (PMID 27161491, 2016). "Others have demonstrated a link between human histological subtypes correlating with specific genetic alterations, such as the inactivation of the CDH1 gene that encodes E-cadherin and is frequently found in lobular carcinomas of the breast." (PMID 26439696, 2015). "Since BC cell lines with high/moderate BCAR4 mRNA expression featured CDH1/E-cadherin mutations, this tumor series was enriched for lobular carcinomas, which lack E-cadherin due to mutation or epigenetic inactivation." (PMID 26317614, 2015). "One patient with lobular carcinoma had two CDH1 mutations and one ERBB2 mutation at ~16% allelic fraction, as well as a distinct set of mutations in PTEN, BRCA2 and PMS2 at ~5% allelic fraction." (PMID 24326041, 2013). "A 51- year old woman, with known CDH1 mutation carrier status and a prior history of lobular breast carcinoma underwent prophylactic total gastrectomy which revealed multifocal intramucosal signet ring cell carcinoma." (PMID 23849133, 2013). "Mutations have been found in the CDH1 gene in about 50% of lobular carcinomas of the breast, while ductal breast cancers show heterogeneous loss of E-cadherin expression, associated with epigenetic transcriptional downregulation." (PMID 19751508, 2009). "Mutational inactivation of CDH1 has been found in 56% of lobular breast carcinomas and 50% of diffuse gastric carcinomas." (PMID 16495925, 2006).
lobular carcinomas (continued). "Somatic mutations in CDH1 occur in lobular breast carcinomas with a frequency ranging from 10–56% (15–20% of invasive lobular carcinomas) and are rare in ductal carcinomas." (PMID 16287501, 2005). "In contrast, the risk of GC in patients with CDH1 germline mutations is reported to be 70% in men, 56% in women, and 42% in women with lobular breast carcinoma by the age of 80 years, indicating a significantly higher incidence of GC than that of other hereditary diseases." (PMID 39895902, 2025). "Molecular alterations in most lobular breast carcinomas involve somatic genetic alterations in the CDH1 gene locus on 16q22.1 resulting in loss of function of the CDH1 gene, loss of IHC staining for E‐cadherin protein, and typical dyscohesive spread of invasive lobular carcinoma cells." (PMID 38335502, 2024). "Loss of the CDH1 gene is central to lobular carcinoma pathogenesis and iterates the important concept of synthetic lethality (in terms of its translational importance), which occurs when there are multiple combined deficiencies in the expression of two or more genes leading to cell death." (PMID 38001750, 2023). "The loss of 16q22.1 in cancer commonly encompasses multiple genes, notably the tumor suppressor gene CDH1, whose mutation may play a role in lobular carcinoma of the breast." (PMID 36037342, 2022). "Though 16q-loss is frequently observed both in ductal and lobular carcinomas (with a slight higher frequency in lobular ones), the CDH1 transcriptional difference between the two histotypes was detectable both in the presence (group A, B1, and D) or the absence of 16q-loss aberrations (CTRL group)." (PMID 33808143, 2021). "Though it was clear that loss-of-function point mutations of CDH1 are cooperating to the decreased functionality of E-cadherin in lobular carcinomas, the transcript levels of lobular CDH1-mutated cancers were not significantly different from those of CDH1-wild type ones." (PMID 33808143, 2021). "Classic lobular carcinomas are usually ER‐positive/HER2‐negative tumors driven by CDH1 alterations and PIK3CA mutations, whereas secretory carcinoma is a low‐grade triple‐negative breast cancer with a recurrent ETV6‐NTRK3 fusion gene and is not driven by PI3K pathway alterations." (PMID 33263939, 2021). "Indeed, a decreased expression of CDH1, at both the protein and transcript levels, was probably underlying the discohesive phenotype of lobular carcinomas." (PMID 33808143, 2021). "Moreover, CDH1 was the only gene belonging to the class of 16q-UnderT that was further decreased in lobular carcinomas in 16q-loss groups." (PMID 33808143, 2021). "A study assessing the risk of CDH1 mutations in patients with gastric and lobular breast carcinoma showed a risk percentage of 60-70% in males and around 80% in females for diffuse gastric cancer and the same study showed 40-50% of lobular breast cancer in women." (PMID 33062523, 2020). "The frequency of CDH1 mutations in PIK3CA-AKT1-PTEN-MT was higher in lobular than in non-lobular carcinoma (73.5 vs. 6.8%), although frequency of CDH1 mutations remained positively associated with PIK3CA-AKT-PTEN-MT after lobular cases were excluded from the analysis." (PMID 32983983, 2020). "Female carriers of the CDH1 mutation also have a predisposition for lobular breast carcinoma." (PMID 23849133, 2013). "Importantly, CDH1 (E-cadherin gene) was downregulated in our lobular carcinomas, and immunohistochemistry confirmed this loss at the protein level within tumors." (PMID 17389037, 2007). "Invasive lobular breast carcinoma, for instance, is characterized by mutations or loss of heterozygosity (LOH) of the CDH1 gene, which encodes E-cadherin, a key epithelial cell–cell adhesion molecule." (PMID 41374933, 2025). "E-cadherin (CDH1 gene) germline mutations are more often linked to diffuse gastric cancer, but they also come with an inherited predisposition to develop lobular breast carcinoma (LBC)." (PMID 38674216, 2024).